HMGA2 (high mobility group AT-hook 2)
Diseases named in the same sentence as HMGA2 in open-access papers (continued):
Sharing a sentence is not in itself a finding about the gene and the disease.
endometrial cancer (continued). "Our study demonstrated that high expression of HMGA2 correlates with poor clinical outcomes in endometrial cancer and that its expression is significantly correlated with clinical stage, tumour grade, and metastasis." (PMID 29391048, 2018). "In order to investigate the carcinogenic effect of HMGA2 in endometrial carcinoma, we determined the baseline expression of HMGA2 in four endometrial cancer cell lines by qRT-PCR." (PMID 29391048, 2018). "Until now, it has been reported that HMGA2 is highly expressed in endometrial cancer tissues and that the overexpression of HMGA2 promotes tumour growth and metastasis." (PMID 29391048, 2018). "Overexpression of HMGA2 promoted proliferation, migration, and invasion and inhibited apoptosis and cell cycle arrest in endometrial cancer cells, indicating that HMGA2 plays an oncogenic role in endometrial carcinoma." (PMID 29391048, 2018). "Based on the TCGA dataset, HMGA2 showed a dramatic overexpression in endometrial cancer tissue compared with that in normal endometrial tissues." (PMID 29391048, 2018). "The results of this study provide compelling evidence on the function and role of HMGA2 in endometrial cancer." (PMID 29391048, 2018). "The results showed that high expression of HMGA2 correlates with a lower survival rate in endometrial cancer." (PMID 29391048, 2018). "The roles of miR-302a-5p and miR-367-3p in the regulation of HMGA2 during the progression of endometrial cancer were investigated using both in vitro and in vivo assays." (PMID 29391048, 2018). "We demonstrated that the expression level of HMGA2 was decreased after overexpression of miR-302a-5p/367-3p in endometrial carcinoma cell lines." (PMID 29391048, 2018). "c and d The expression of RUNX1 was positively correlated with the expression of HMGA2 in endometrial carcinoma tissue." (PMID 29391048, 2018). "In this study, we identified two novel aberrantly-expressed miRNAs, miR-302a-5p and miR-367-3p, that modulate the malignant behaviour of endometrial carcinoma cells through the suppression of HMGA2 expression." (PMID 29391048, 2018). "To analyse the overall survival curves for the endometrial carcinoma patients in reference to HMGA2 mRNA expression, we retrieved and analysed the data from the TCGA dataset." (PMID 29391048, 2018). "In summary, this study demonstrated that miR-302a-5p/367-3p mediated the ability of HMGA2 to regulate the malignant behaviour of endometrial carcinoma cells." (PMID 29391048, 2018). "Compared to normal tissues, the methylation level of the HMGA2 promoter in endometrial cancer was significantly reduced, especially in stage III tumors, where the decrease was most pronounced, leading to reduced chromosomal stability and increased tumorigenesis." (PMID 40703517, 2025). "Some studies have also shown that high expression of HMGA2 weakened the inhibitory effect of miR-302a-5p/367-3p on the malignant behavior of endometrial cancer cells, thereby promoting the progression of EC and being associated with poor prognosis in EC patients." (PMID 40703517, 2025). "Given that most endometrial carcinomas are adenocarcinomas where immunotherapy-chemotherapy combinations constitute first-line therapy for advanced/recurrent disease, we pharmacologically profiled HMGA2 using GDSC database." (PMID 40703517, 2025). "There has been previous evidence that MiR‐302a‐5p/367‐3p regulates HMGA2, which may serve as a marker for survival for endometrial cancer patients and a therapeutic target for treating it." (PMID 37283291, 2023). "In addition, miR-302a-5p/367-3p mediated the ability of HMGA2 to regulate the malignant behavior of endometrial carcinoma cells." (PMID 35408691, 2022). "Additionally, the correlations between the expression of miR-302a-5p/367-3p and HMGA2 protein in endometrial cancer patients were analysed." (PMID 29391048, 2018). "Therefore, overexpression of miR-302a-5p/367-3p or knockdown of HMGA2 reversed EMT in endometrial cancer cells." (PMID 29391048, 2018).
endometrial cancer (continued). "Thus, we confirmed that in endometrial cancer cells, HMGA2 is a functional target of miR-302a-5p/367-3p in the regulation of EMT-associated proteins." (PMID 29391048, 2018). "Therefore, miR-302a-5p/367-3p likely regulates extracellular matrix remodelling during invasion and distant metastasis in endometrial cancer by regulating the miR-302a-5p/367-3p-HMGA2 axis." (PMID 29391048, 2018). "However, the mechanisms by which HMGA2 regulates the biological characteristics of endometrial cancer as well as the factors involved remain undefined." (PMID 29391048, 2018). "In addition, miR-302a-5p/367-3p suppressed the malignant behaviour of endometrial carcinoma cells via the inhibition of HMGA2 expression." (PMID 29391048, 2018). "Moreover, the expression of RUNX1 was positively correlated with the expression of HMGA2 in endometrial carcinoma tissue." (PMID 29391048, 2018). "To verify whether miR-302a-5p/367-3p controls the HMGA2-mediated regulation of the malignant behaviour of endometrial carcinoma cells, we investigated the exact contribution of the miR-302a-5p/367-3p-HMGA2 axis on Ishikawa and HEC-1A cells." (PMID 29391048, 2018). "We further investigated the effect of the binding of miR-302a-5p/367-3p to HMGA2 on the malignant behaviour of endometrial carcinoma in vitro and found that the overexpression of HMGA2 attenuated the suppressive effect of miR-302a-5p/367-3p on the malignant behaviour of endometrial cancer cells." (PMID 29391048, 2018). "In endometrial cancer, cell proliferation and the EMT were promoted after HMGA2 overexpression which resulted from miR-302a-5p/367-3p downregulation." (PMID 38361784, 2024). "In the endometrial cancer cell lines Ishikawa and HEC-1A, the overexpression of miR-302a-5p/367-3p significantly inhibited the expression of HMGA2 mRNA." (PMID 29391048, 2018). "The effect of HMGA2 on the proliferation of the endometrial cancer cell lines Ishikawa and HEC-1 was studied using CCK-8 and EdU assays after overexpressing or knocking down HMGA2." (PMID 29391048, 2018). "The results of qRT-PCR and western blotting showed that the expression level of HMGA2 was higher in endometrial carcinoma tissues than that in normal endometrial tissues." (PMID 29391048, 2018). "We retrieved and analysed the data from the TCGA dataset to determine the relationship between the protein levels of HMGA2 and RUNX1 in endometrial carcinoma, and the results indicated that the expression of RUNX1 was positively correlated with the expression of HMGA2." (PMID 29391048, 2018). "Thus, knockdown of HMGA2 exerts tumour-suppressive effects on Ishikawa and HEC-1A cells, while overexpression of HMGA2 promotes the malignant behaviours of these cells, indicating the role of HMGA2 as an oncogene in endometrial cancer." (PMID 29391048, 2018).
leiomyosarcoma (14 papers, 2010 to 2025). An uncommon, aggressive malignant smooth muscle neoplasm, usually occurring in post-menopausal women. "Although most ULMS do not share common genetic drivers with ULs, MED12 hotspot mutations, HMGA2 overexpression and FH inactivation have been shown to occur in some ULMS cases, suggesting that leiomyosarcomas may originate from Uls." (PMID 40016412, 2025). "To test whether let-7 microRNAs could regulate other predicted target genes in addition to HMGA2 in ULMs, we examined the expression of several predicted let-7 target genes in the ectopically induced presence or absence of let-7 microRNAs in uterine ULMs and leiomyosarcoma cell lines in vitro." (PMID 20808773, 2010).
lymph node metastasis (14 papers, 2012 to 2025). "Both TCGA and IHC results showed that HMGA2 expression was associated with lymph node metastasis and clinical stage." (PMID 37283291, 2023). "HMGA2 acts as an independent prognostic marker associated with lymph node metastasis and a significantly shorter OS in PDAC." (PMID 35664782, 2022). "In cervical AC patients, high expression of HMGA2 was associated with positive lymph node metastasis (p=0.036) and elevated ER-α36 expression (p=0.00)." (PMID 34336701, 2021). "Clinicopathological analysis indicated that HMGA2 expression was associated with clinical stage (P = 0.001), lymph node metastasis (P = 0.000), histological differentiation (P = 0.002) and survival (P = 0.000)." (PMID 26818837, 2016). "Our results show that overexpression of HMGA2 is closely associated with lymph node metastasis and immunohistochemical staining indicate that both HMGA2 and Snail are upregulated and co-localized in the nuclear." (PMID 26818837, 2016). "In addition, a close association was found between HMGA2 expression and lymph node metastasis, clinical stage, and tissue subtype." (PMID 37283291, 2023). "Furthermore, HMGA2 expression was linked to lymph node metastases (p < 0.001) as well as distant metastases (p = 0.02), and pathologic stage (p = 0.02)." (PMID 37283291, 2023). "In addition, HMGA2 expression was associated with tissue subtype, lymph node metastasis, and clinical stage." (PMID 37283291, 2023). "Furthermore, we showed that high HMGA2 expression is associated with lymph node metastasis, distant metastasis, and poor prognosis in OSCC patients." (PMID 31109142, 2019). "Out of the 444 samples, HMGA2 amplification is observed in 4 samples in bone metastasis and 11 samples in lymph node metastasis, which comes to a percentage of 2.5% HMGA2 amplification in bone and lymph node metastasis (link)." (PMID 39123360, 2024). "Collectively, based on our findings, HMGA2 expression appears to be correlated with PRCC tissue subtypes, cell pleomorphisms, and significantly associated with clinical stage and lymph node metastasis." (PMID 37283291, 2023). "Immunohistochemistry of 91 pairs of PRCC tissues demonstrated that HMGA2 was associated with PRCC tissue subtype and was positively correlated with clinical stage and lymph node metastasis." (PMID 37283291, 2023). "According to our results, HMGA2 overexpression was significantly linked to advanced TNM stage (stage III/IV), positive lymphovascular space invasion, distant metastasis, and lymph node metastasis." (PMID 29416690, 2018). "Several studies have shown that high levels of HMGA2 expression are associated with survival in/ and the clinicopathologic features of GC patients, including TNM stage, deep of invasion, and lymph node metastasis." (PMID 29245994, 2017). "In addition, the prognostic value of HMGA2 expression in patient was also evaluated according to the lymph node metastasis, clinical stage and T stage." (PMID 26818837, 2016). "As HMGA2 expression was positively related with lymph node metastasis and metastasis to distant organs contributes to poorer survival, next we investigate the effect of HMGA2 on the migration and invasion of Cal27 epithelial tongue cancer cell and UM1 mesenchymal tongue cancer cell." (PMID 26818837, 2016). "Therefore, clinically, HMGA2 overexpression may be relevant in bone and lymph node metastasis and may be increased in tissue that has been treated with anti-androgens." (PMID 39123360, 2024). "In cervical SCC patients, clinicopathological characteristic analysis showed HMGA2 expression was correlated with FIGO stage (p=0.012), DSI (p=0.03), lymph node metastasis (p=0.005) and ER-α36 expression (p<0.001)." (PMID 34336701, 2021).
lymph node metastasis (continued). "Cox multivariate analysis showed that the largest tumor diameter was ≥2 cm, that lymph node metastasis had occurred, invading the surrounding tissues and organs, and that HMGA2-positive expression or CD9-negative expression was negatively correlated with the postoperative survival time of patients." (PMID 22613496, 2012).
breast tumor (13 papers, 2015 to 2024). "In mouse xenografts, it was further shown that HMGA2 promotes breast tumor growth, survival, and metastasis by inducing syndecan-2 (SDC2) via a miR-200-independent mechanism." (PMID 33668453, 2021). "Previously, we demonstrated increased HMGA2 expression in breast tumor tissues compared to normal tissues." (PMID 33668453, 2021). "The HMGA2/miR-200b/LOX axis plays an important role in the initial stages of breast tumor cell invasion and metastasis." (PMID 33668453, 2021). "HMGA2 has been suggested to mediate breast tumor metastasis by promoting the expression of LOX and syndecan-2." (PMID 25868853, 2015). "When a breast tumor is first developing, let-7a silences its target genes, HMGA2 (high-mobility group AT-hook 2) and H-Ras (transforming protein p21), in order to perform BT-IC stem cell-like functions." (PMID 38812786, 2024). "Not only did over expression of HMGA2 imparted metastatic traits in non-metastatic breast tumor in mouse model but also suppression of HMGA2 lead to reduced tumor multiplicity." (PMID 33639654, 2021). "Our recent study demonstrated that HMGA2 and CD133 positively correlate in breast tumors." (PMID 33668453, 2021). "Our findings suggest that the assessment of rearrangements involving PLAG1 or HMGA2 in breast PAs, and of MAML2 rearrangements in breast MECs, might be used as ancillary tools to aid in the diagnosis of these rare breast tumors." (PMID 32550265, 2020). "Of note, there were also no small deletions of the HMGA1 and HMGA2 loci indicating rearrangements of these genes or chromosomal bands 6p21 or 12q14-15, respectively, as described in other biphasic breast tumors." (PMID 33292379, 2020). "A possible mechanism is that the ZNF350/BRCA1/CtTB-interacting protein complex represses the expression of angiopoietin-1 (ANG1) and high-mobility group AT-hook 2 (HMGA2), which are commonly involved in the proliferation and vascularization during breast tumor formation." (PMID 30613364, 2018). "A possible explanation is that the complex CtIP(CtTB interacting protein)/ZNF350/BRCA1 complex represses the expression of angiopoitin-1 (ANG1) and high-mobility group AT-hook 2 (HMGA2), which are commonly involved in the proliferation and vascular formation of breast tumours." (PMID 29291027, 2017).
leukemia (13 papers, 2003 to 2025). A malignant (clonal) hematologic disorder, involving hematopoietic stem cells and characterized by the presence of primitive or atypical myeloid or lymphoid cells in the bone marrow and the blood. "Reactivation of HMGA1 and HMGA2 has been demonstrated in a wide range of malignancies including leukemia." (PMID 38601080, 2024). "In our study, the overexpression of HMGA2 accelerated the S–G2/M transition in the GC cells, instead of the G0/G1 phase, which was consistent with the findings in leukemia." (PMID 34513922, 2021). "HMGA2 expression is upregulated in MLL-AF4 leukaemia cell lines which leads to an increased cell proliferation that is dependent on the hypermethylation of the miR-let-7b promoter." (PMID 28819864, 2018). "We therefore explored expression of HMGA2 in different sub-types of ALL, and found it upregulated in KMT2A::AFF1-driven leukemia and enriched in infants." (PMID 40646135, 2025). "The epigenetic abnormalities result in the upregulation in leukaemia blasts of an array of genes which are normally expressed in haematopoietic stem cells, such as HOXA9, MEIS1, HMGA2 and RUNX1." (PMID 28819864, 2018). "Fetal-specific genes (HMGA2) have been identified in a rare HSC-like fraction of KMT2A-r infant leukemia, and IGF2BP1 maintains LSC by regulating HOXB4, MYB, and ALDH1A1 in pediatric leukemia cell lines." (PMID 38601080, 2024). "Finally, we determined the functional relevance of Hmga2 and Flt3 co-expression in G12D/E2-KO HSPCs by measuring the colony-forming activity, which is commonly used to assess hematopoietic or leukemia stem cell activity, with or without FLT3 inhibition and/or HMGA2 depletion." (PMID 34732703, 2021). "In the ALD trials there were some clones showing clonal dominance with over-representation of the insertion site near SMG6, CCND2, and HMGA2, but this has not led to development of leukemia and may be transient, as was reported for a SIN LV vector used for treating β-thalassemia." (PMID 32322605, 2020).
lung adenocarcinoma (13 papers, 2017 to 2026). A carcinoma that arises from the lung and is characterized by the presence of malignant glandular epithelial cells. "Earlier, circASPH was reported to act as a tumour‐promotor through targeting miR‐370/HMGA2 axis in lung adenocarcinoma, however, the potential role of circASPH in PCOS is still unclear." (PMID 33372369, 2022). "To investigate the downstream circRNAs of HMGA2 in lung adenocarcinoma, we first used a lentivirus vector to stably overexpress HMGA2 in lung adenocarcinoma cell line A549." (PMID 32719345, 2020). "In this study, using RNA sequencing, we identified specific expression patterns of HMGA2-related circRNAs in the human lung adenocarcinoma cell line A549." (PMID 32719345, 2020). "We further demonstrated that circASPH, which was directly regulated by HMGA2 and Twist1, promoted malignant phenotypes in lung adenocarcinoma by sponging miR-370, and the oncogenic effects of circASPH were HMGA2-dependent." (PMID 32719345, 2020). "The findings that circASPH was upregulated in lung adenocarcinoma tissues, and was directly regulated by HMGA2 and Twist1 prompted us to consider circASPH as an oncogene in lung adenocarcinoma." (PMID 32719345, 2020). "Some of these genes (HMGA2, MMP13, BIRC7, and PLA2G2D) have been reported to be overexpressed in various cancers, including lung adenocarcinoma, and are associated with tumor progression and metastasis, supporting their potential as biomarkers for PD-1 immunotherapy." (PMID 41529246, 2026). "Moreover, Group 1 spheroids express HMGA2, a functional marker of metastatic competency in lung adenocarcinoma." (PMID 37728504, 2023). "Interestingly, some researchers found an opposite phenomenon that NKX2-1 can constrain lung adenocarcinoma in part by repressing the embryonically restricted chromatin regulator Hmga2." (PMID 36203529, 2022). "Overall, this study revealed the oncogenic functions of the HMGA2-circASPH-HMGA2 axis in lung adenocarcinoma and may be useful in developing circRNA-based therapeutic strategies for lung adenocarcinoma." (PMID 32719345, 2020). "We speculated that tumor-associated macrophages may regulate TTF-1 expression by producing TGF-β and that the TTF-1/HMGA2/EFGR pathway may play a role in the carcinogenesis of lung adenocarcinoma." (PMID 29079814, 2017). "In lung adenocarcinoma, circASPH could be regulated by HMGA2 to promote tumor growth." (PMID 35795047, 2022). "The TTF-1, miR33a and HMGA2 may have cross talk in regulation of the lung adenocarcinoma." (PMID 29079814, 2017). "In addition, miR-26a and HMGA2 mRNA are inversely correlated in gallbladder cancer (GBC) tissues, and miR-26a reduces the proliferation of GBC cells and human lung adenocarcinoma cells, which increases the sensitivity to cisplatin treatment via HMGA2." (PMID 31979076, 2020).